LIF (LIF interleukin 6 family cytokine)
Diseases named in the same sentence as LIF in open-access papers (continued):
Sharing a sentence is not in itself a finding about the gene and the disease.
pancreatic cancer (continued). "LIF has emerged as a key target in pancreatic cancer (PDAC) due to its role in promoting chemoresistance by driving tumor progression and promoting an immunosuppressive tumor microenvironment." (PMID 39857986, 2025). "To further clarify the regulatory role of CTHRC1 on LIF in CAFs, we first examined the differential expression of LIF in CAFs, pancreatic cancer cell lines, and human pancreatic stellate cells (HPSCs)." (PMID 40751418, 2025). "Its role in supporting cancer progression positions LIF as a potential therapeutic target for pancreatic cancer." (PMID 38756774, 2024). "In pancreatic cancer cells, LIF has been reported to activate the JAK/STAT3 pathway, which upregulates genes involved in cell proliferation and survival." (PMID 39451257, 2024). "Leukemia inhibitory factor (LIF), a member of the interleukin-6 cytokine family, mediates signal transduction between pancreatic cancer cells and stellate cells, emerging as a pivotal factor in the regulation of cell differentiation, renewal, and survival." (PMID 38756774, 2024). "For example, LIF acts in a paracrine manner on pancreatic cancer cells to support tumor progression." (PMID 38789520, 2024). "Altogether, circFARP1 promotes CAF-mediated LIF secretion and thus induces gemcitabine resistance of pancreatic cancer via LIF-STAT3 pathway." (PMID 38933287, 2023). "In the organoids produced by pancreatic cancer patients, LIF, IL-8, and growth differentiation factor 15 (GDF15) are prominently up-regulated in cachectic patients." (PMID 35740622, 2022). "CAF-secreted LIF inhibits pancreatic cancer cell differentiation and maintains their stemness, while blocking LIF using neutralizing antibodies and knocking down LIFR both prolong the survival of KPf/fCL multiple mutant mice." (PMID 35740622, 2022). "The inflammatory cytokines TNF-α and LIF influence the CXCL-8 expression in pancreatic cancer progression." (PMID 35887223, 2022). "Aside from the LIF serum levels, a raised LIF concentration was observed in pancreatic cancer tissue samples compared to chronic pancreatitis or benign lesions (PanIN) and inversely correlated with the tumor differentiation level." (PMID 35565450, 2022). "Neutralizing LIF attenuates pancreatic cancer development and improves the sensitivity of cancer cells to drugs." (PMID 35740622, 2022). "A recent study showed that LIF was the key mediator for maintaining the inflammatory CAF phenotype in pancreatic cancer, which was upregulated by tumor-secreted IL-1-induced NF-κB signaling activation in CAFs." (PMID 35045883, 2022). "It has been reported that LIF is frequently overexpressed in many cancer types, including pancreatic cancer, colon cancer, and prostate cancer." (PMID 35440095, 2022). "The key mediators of LIF for the iCAF phenotype and TGFβ for the myCAF phenotype in pancreatic cancer are modulated by CAV1, which would explain the contradictory role of CAV1 in the TME, and the detailed mechanisms require further analysis." (PMID 35045883, 2022). "Increased serum LIF is a biomarker to predict lymph node metastasis and distant metastasis in pancreatic cancer patients." (PMID 35159011, 2022). "Within pancreatic cancer tumors and mouse models, both cancer and stromal cells express LIF, but only stromal cells, mainly macrophages and fibroblasts, secrete LIF." (PMID 35204717, 2022). "Regarding the specific source of LIF, our results found that the expression of LIF in pancreatic cancer cell lines was significantly lower than that of CAFs." (PMID 35045883, 2022). "Additional studies of pancreatic cancer found that ROC analysis of serum LIF levels was more effective than other biomarkers (CA199 and CEA) at predicting metastasis." (PMID 35204717, 2022). "Further clarification is needed to understand the precise role of LIF/LIFR signaling in pancreatic cancer." (PMID 35159011, 2022).
pancreatic cancer (continued). "Of note, pancreatic carcinoma cells constitutively express LIF and its heterodimer receptor (LIFR and gp130), and TNFα, IL1β or LIF itself enhanced the expression of LIF mRNA." (PMID 35565186, 2022). "Secreted by CAFs in the microenvironment, LIF was shown to bind on the surface of pancreatic cancer cells, induce STAT3 phosphorylation, and ultimately stimulate PDAC growth and progression." (PMID 33630157, 2021). "LIF silencing by shRNA or CRISPR/Cas9 led to a loss of the ability of human and mouse pancreatic cancer cell lines to grow as spheres, an effect which was reversible after exposure to culture medium with LIF." (PMID 33630157, 2021). "In a human in vitro pancreatic cancer model, LIF expression was highly correlated with increased YAP activity." (PMID 34395259, 2021). "LIFR inhibition has already been found to effectively block LIF-induced perineural invasion in pancreatic cancer cell lines and in mouse models." (PMID 33630157, 2021). "In general, LIF was found to be overexpressed in human pancreatic carcinomas relative to normal tissue, and that in a pan-cancer analysis LIF was significantly more upregulated in cancers with a mutation in KRAS." (PMID 34395259, 2021). "CAFs co-cultured with organoids derived from pancreatic cancer patients secrete IL-6, IL-11, and leukemia inhibitory factor (LIF), and these ligands activate a signal transducer and activator of transcription 3 (STAT3) in organoids." (PMID 33333727, 2020). "It was observed in pancreatic cancer that IL-1 induces LIF expression and downstream JAK/STAT activation to generate inflammatory CAFs." (PMID 33182777, 2020). "Treatment with LIF-neutralizing antibody at 10 mg/kg/mouse before injection of human pancreatic cancer cells, followed by treatment twice a week, successfully prevented tumor establishment in a pancreatic xenograft model." (PMID 31296870, 2019). "Our results suggest that blocking LIF and its specific downstream signaling pathway can provide an alternative approach to improving therapeutic outcomes of pancreatic cancer." (PMID 31296870, 2019). "Blocking LIF activity by antibody inhibited the sphere-forming ability of mouse pancreatic cancer cells." (PMID 31296870, 2019). "As expected, the presence of LIF enhanced the number of viable spheroid cells derived from human pancreatic cancer cells when compared with controls." (PMID 31296870, 2019). "In this regard, we present data showing KRAS regulates expression of LIF in mouse and human pancreatic cancers." (PMID 31296870, 2019). "Knocking down LIF by shRNA repressed the tumor initiation and growth rate of human pancreatic cancer cell line in xenograft models." (PMID 31296870, 2019). "Our data suggest a crucial role of LIF in KRAS-driven pancreatic cancer and that blockade of LIF by neutralizing antibodies represents an attractive approach to improving therapeutic outcomes." (PMID 31296870, 2019). "Depleting LIF expression by genetic means or blocking its activity by antibody prevents pancreatic tumor initiations and re-sensitizes cancer cells to Gemcitabine." (PMID 31296870, 2019). "LIF functions as a growth factor in pancreatic carcinoma cells and the crosstalk between tumor cells and fibroblasts confer pro-invasive properties, in part, mediated by LIF signaling." (PMID 30899415, 2019). "In preclinical models of pancreatic cancer, it was observed that an increased ratio of myCAF to iCAF induced by leukemia inhibitory factor (LIF) inhibited cancer cell proliferation through deposition of ECM proteins that in turn resulted in regression of tumor growth." (PMID 40805183, 2025). "Moreover, LIF is the most important molecule in activating the STAT3 signaling pathway in pancreatic cancer." (PMID 40751418, 2025).
pancreatic cancer (continued). "Finally, to further explore and verify that CTHRC1 in CAFs activates the STAT3 signaling pathway in pancreatic cancer cells by regulating LIF, we cocultured CAFs‐CM with pancreatic cancer cells and added the LIF inhibitor EC330 at various concentrations." (PMID 40751418, 2025). "To further explore the detailed molecular mechanism and signaling pathway by which CTHRC1 in CAFs regulates the progression of pancreatic cancer, we reviewed the literature and found that existing studies have confirmed that LIF mainly acts by activating the STAT3 signaling pathway." (PMID 40751418, 2025). "To further clarify the detailed mechanism of CTHRC1 in CAFs in pancreatic cancer, we found that LIF may be one of the key downstream molecules of CTHRC1 in CAFs regulating pancreatic cancer progression by RNA‐sequence results and database analysis." (PMID 40751418, 2025). "Furthermore, CCK‐8, colony formation, and Transwell migration assays revealed that CTHRC1 in CAFs promotes pancreatic cancer cell proliferation and migration through LIF‐dependent regulation." (PMID 40751418, 2025). "Nevertheless, LIF also plays a role in pancreatic cancer cell proliferation." (PMID 39451257, 2024). "The possibility of targeting LIF as a method of combatting chemoresistance has been studied extensively in pancreatic cancer, where genetic and pharmacologic inhibition of LIF signaling has been seen to improve chemotherapy efficacy in studies of cell lines and in mouse models." (PMID 35204717, 2022). "Impressively, we could hardly detect the secretion of LIF in the supernatant of pancreatic cancer cells." (PMID 35045883, 2022). "Overexpression of circFARP1 in CAFs confers GEM resistance in pancreatic cancer cells by enhancing the expression and secretion of LIF in CAFs, thereafter activating the STAT3 signaling pathway and increasing the expression of several GEM resistance-associated factors, including ABCC2, CDA and SOX2." (PMID 35045883, 2022). "Furthermore, our clinical data highlighted the prognostic value of the circFARP1/CAV1/miR-660-3P/LIF axis for predicting GEM resistance in patients with pancreatic cancer." (PMID 35045883, 2022). "Moreover, experimental models of pancreatic cancer have shown that CAF-derived LIF activated pancreatic cancer cells and that it was correlated with tumor progression." (PMID 34203869, 2021). "Therefore, blockade of LIF provides an attractive approach to improving therapeutic outcomes of pancreatic cancer." (PMID 33408779, 2021). "This engineered ‘ligand trap’, fused to an antibody Fc-domain, has ~50-fold increased affinity (~20 pM) and improved LIF inhibition compared to wild-type LIFR-Fc, potently blocks LIF-mediated effects in pancreatic cancer cells, and slows the growth of pancreatic cancer xenograft tumors." (PMID 33846527, 2021). "To understand whether LIF and IL-6 have different effects on the activation of YAP/TAZ-TEAD in pancreatic cancers, we treated serum-starved human pancreatic cancer cells with IL-6 or LIF at 100 ng/mL." (PMID 31296870, 2019). "Moreover, knocking down LIF by shRNA impaired the ability of human pancreatic cancer cell line to grow as spheres in 3D culture." (PMID 31296870, 2019). "Next, we examined the functional roles of LIF in oncogenic KRAS-driven pancreatic cancers." (PMID 31296870, 2019). "Similarly, knocking out LIF by CRISPR/Cas9 enhanced phosphorylation of YAP at Ser127 in mouse pancreatic cancer cells." (PMID 31296870, 2019). "Furthermore, IL-6 showed a stronger ability to activate/phosphorylate STAT3 at Tyr705 than did LIF or another IL-6 family member, IL-11, in human pancreatic cancer cells." (PMID 31296870, 2019). "Moreover, LIF-neutralizing antibodies synergize with gemcitabine to eradicate established pancreatic tumors in a syngeneic, KrasG12D-driven, PDAC mouse model." (PMID 31296870, 2019).
pancreatic cancer (continued). "Finally, to further confirm that CTHRC1 in CAFs activates STAT3 signaling in pancreatic cancer cells via LIF regulation, we cocultured CTHRC1‐overexpressing CAFs‐CM with pancreatic cancer cells in the presence of the LIF inhibitor EC330 and STAT3 inhibitor Stattic." (PMID 40751418, 2025). "Similarly, LIF depletion by genetic means or by neutralizing antibodies prevented engraftment in pancreatic xenograft models and synergized with gemcitabine to eradicate established pancreatic tumors in a syngeneic, KrasG12D-driven PDAC mouse model." (PMID 37174079, 2023). "Because these data suggest that the LIF/LIFR pathway is modulated in PDAC tissues, we then investigated whether LIF/LIFR expression undergoes the same regulation in two pancreatic cancer lines, MIA PaCa-2 and PANC-1, which are widely used as in vitro models for PDAC." (PMID 36359879, 2022). "Finally, to further investigate whether CAF‐derived CTHRC1 activates the STAT3 signaling pathway in pancreatic cancer cells via LIF, we cocultured PDAC cells with conditioned medium from CTHRC1‐overexpressing CAFs (CAFs‐CM) in the presence of the STAT3‐specific inhibitor Stattic." (PMID 40751418, 2025). "Our current study demonstrates that in pancreatic cancer, CTHRC1+ CAFs primarily rely on the LIF/STAT3 signaling pathway to promote pancreatic cancer cell growth and metastasis." (PMID 40751418, 2025). "KP4 pancreatic cancer cell line was chosen as the signaling sender because it is known to express a high level of HGF and a low level of LIF, which was confirmed by analysis of the CM of KP4 cells." (PMID 37438365, 2023). "As CAV1 mediates caveola-mediated exocytosis, CAV1 stabilization enhances LIF exocytosis from CAFs and activates the JAK–STAT signaling pathway in pancreatic cancer cells." (PMID 36467402, 2022). "Together, these data demonstrate that LIFR inhibition reverses pancreatic cancer cell proliferation and EMT promoted by LIF/LIFR signalling." (PMID 36359879, 2022). "Mechanistically, circFARP enhances leukemia inhibitory factor (LIF) expression by decoying miR-660-3p, and LIF secreted from CAFs induces gemcitabine resistance in pancreatic cancer cells by activating the LIF/STAT3 pathway." (PMID 36467402, 2022). "We further determined that the circFARP1/LIF axis remarkably increased the expression of GEM resistance-related genes, such as ABCC2, CDA, and SOX2, and induced GEM resistance in pancreatic cancer cells." (PMID 35045883, 2022). "Our results suggest that, even though IL-6 and LIF share STAT3 as a downstream effector, they have distinct functional roles in human pancreatic cancer cells harboring mutant KRAS." (PMID 31296870, 2019). "Our data indicate that LIF is stimulated by KRAS and further it plays an important role in facilitating KRAS to drive pancreatic cancer." (PMID 31296870, 2019). "We next expressed Tet-inducible shRNA against human LIF in multiple human pancreatic cancer cell lines, to study the role(s) LIF plays in KRAS-driven pancreatic cancer maintenance." (PMID 31296870, 2019). "In human pancreatic tumor specimens, LIF is negatively correlated with phospho-YAP at Ser127, suggesting the clinical relevance of LIF-YAP signaling circuitry identified." (PMID 31296870, 2019). "Although a Phase 2 combination human clinical trial is underway, primarily for the treatment of metastatic pancreatic cancer, effective small molecule inhibitors targeting LIF in HCC are still lacking." (PMID 40416597, 2025). "Similarly, we also examined the effect of adding the LIF inhibitor to CAFs‐CM overexpressing CTHRC1 on the proliferation and migration of pancreatic cancer cells using CCK‐8, colony formation, and Transwell migration assays." (PMID 40751418, 2025). "In pancreatic cancer, LIF secreted by CAFs binds to LIFR on the surface of pancreatic cancer cells and then activates the downstream STAT3 signaling pathway to play its biological role in promoting the progression of pancreatic cancer and chemoresistance." (PMID 40751418, 2025).
pancreatic cancer (continued). "In line with this, we previously showed that pancreatic tumor organoids from cachectic and non-cachectic pancreatic cancer patients expressed variable levels of known cachexia-associated cytokines, including IL-6, TNF-α, IL-8, IL-1α, IL-1β, Mcp-1, and LIF." (PMID 38339292, 2024). "Genetic ablation of LIFR and pharmacologic LIF blockade in the KPC mouse model demonstrated that LIF mainly acts on pancreatic cancer cells to facilitate tumor progression but not initiation." (PMID 37174079, 2023). "Gene expression profile analysis and further experiments showed that circFARP1 conferred GEM resistance by enhancing LIF expression and secretion in CAFs, thereafter increasing the expression of ABCC2, CDA and SOX2 by activating the STAT3 signaling pathway in pancreatic cancer cells." (PMID 35045883, 2022). "In addition, proteomic studies identified LIF as the key paracrine factor responsible for interactions between TME and pancreatic cancer cells." (PMID 33630157, 2021). "In addition, leukemia inhibitory factor (LIF) inhibits the activity of the Hippo-signaling pathway and subsequently increases YAP transcriptional activity in KRAS-driven pancreatic cancer." (PMID 33408779, 2021). "As a paracrine factor, LIF binds to the heterodimer of LIFR and gp130 on the surface of pancreatic cancer cells, activates the JAK/STAT3 pathway and ultimately induces transcription of genes which are known to regulate cell cycle, apoptosis, angiogenesis and invasion." (PMID 33630157, 2021). "In addition, the depletion of LIF significantly enhanced overall survival rate in FVB/n mice, which received syngeneic transplantation of pancreatic cancer cells." (PMID 31296870, 2019). "Multiple pancreatic cancer cell lines where LIF had been knocked down were first seeded in 3D culture with or without LIF, and viable spheroid cells were quantified by CellTiter Glo assay on the fourteenth day." (PMID 31296870, 2019). "Treatment with LIF antibody had the same effects on activation of Hippo-signaling pathway in human pancreatic cancer cells without altering their KRAS expression and ERK activity." (PMID 31296870, 2019). "Furthermore, histochemical staining revealed that expressions of LIF and phospho-YAP at Ser127 are negatively correlative in human pancreatic tissues (Biomax human pancreatic cancer tissue array PA484 and PAN241)." (PMID 31296870, 2019). "Therefore, our results reveal the role of CTHRC1 in CAFs in pancreatic cancer, and the CTHRC1/LIF/STAT3 signaling axis may be a promising prognostic marker and therapeutic target for patients with pancreatic cancer." (PMID 40751418, 2025). "Since there are robust evidence that the LIF/LIFR pathway exerts a pro-oncogenic role in PDAC cell lines, and because FXR expression is increased in human PDAC tissues, we have focused our attention on the role that natural and synthetic steroids exert in modulating pancreatic cancer cell lines." (PMID 36998446, 2023). "Furthermore, inhibition of MEK, but not AKT, by small molecules downregulated the expression of LIF in human pancreatic cancer cell line Panc1.0, suggesting that the MEK/ERK signaling pathway is essential for regulation of LIF expression by KRAS." (PMID 31296870, 2019). "Furthermore, we show that LIF, but not IL-6, inhibits the activity of the Hippo-signaling pathway in pancreatic cancer cells." (PMID 31296870, 2019). "Human pancreatic cancer cell lines established at our department were cultured in CSC-inducing media containing epidermal growth factor (EGF), basic fibroblast growth factor (bFGF), leukemia inhibitory factor (LIF), neural cell survivor factor-1 (NSF-1), and N-acetylcysteine." (PMID 25118635, 2014). "In addition, MSC‐1/AZD0171 neutralizing LIF mAb, although in Phase 2 combined human clinical trial (NCT049999690), is primarily intended for the treatment of metastatic pancreatic cancer, and there is still a lack of effective small molecule inhibitors for cytoplasmic LIF in HCC." (PMID 40416597, 2025).